ASPRV1 (aspartic peptidase retroviral like 1)
Description:
Protease responsible for filaggrin processing, essential for the maintenance of a proper epidermis organization.
Synonyms: SASPase; TAPS; FLJ25084
Tractability: Antibody: UniProt predicts a signal peptide or a membrane-spanning region.
Gene: Protein-coding gene on chromosome 2 (69,960,089 to 69,961,631, reverse strand). Ensembl gene ENSG00000244617.
Subcellular location: Membrane
Subcellular location (Human Protein Atlas): Cytosol
Gene Ontology:
Molecular function: aspartic-type endopeptidase activity
Biological process: protein processing; skin development; proteolysis
Cellular component: membrane
Genetic constraint (gnomAD): Loss-of-function variants: 10 observed, 13.54 expected, observed/expected ratio (o/e) 0.74, 90% interval 0.46 to 1.25. The upper end of that interval is the gene's LOEUF score, 1.25, which puts it in group 5 of 6, group 1 being the genes least tolerant of losing a copy. Missense variants: 299 observed, 338.31 expected, observed/expected ratio (o/e) 0.88, 90% interval 0.8 to 0.97. Synonymous variants: 136 observed, 146.57 expected, observed/expected ratio (o/e) 0.93, 90% interval 0.81 to 1.07.
Homologues: Orthologues: chimpanzee ASPRV1 (98% identical), macaque ASPRV1 (97% identical), pig ASPRV1 (88% identical), rabbit ASPRV1 (83% identical), rat Asprv1 (82% identical), mouse Asprv1 (80% identical).
Diseases named in the same sentence as ASPRV1 in open-access papers:
ASPRV1 is named in the same sentence as 11 diseases in open-access papers, as found by Europe PMC text mining. Sharing a sentence is not in itself a finding about the gene and the disease. The quoted sentences say what the papers report.
ichthyosis (6 papers, 2017 to 2024). Disorders of cornification that are characterized by visible scaling and/or hyperkeratosis of most or all of the skin. "Such mutations were identified by sequencing of ASPRV1 gene from subjects with skin disorders such as ichthyosis, atopic dermatitis, eczema, or clinically dry skin." (PMID 39098535, 2024). "A cleavage site mutation was also identified at the C terminus of ASPRV1 in a German Shepherd dog with ichthyosis, as well." (PMID 39098535, 2024). "An autosomal dominant form of ichthyosis in a German shepherd dog was caused by a missense variant in ASPRV1 encoding a protease required for the posttranslational processing of profilaggrin." (PMID 36251712, 2022). "Intriguingly, mutations in Asprv1, also acutely upregulated upon Stat3 oxidation (60-fold), are implicated in ichthyosis." (PMID 33332446, 2020). "In conclusion, with the identification of a dominant de novo missense variant in the ASPRV1 gene of an ichthyotic dog, we present a new candidate gene for ichthyosis." (PMID 28249031, 2017). "In the present study we identified a de novo missense variant in the canine ASPRV1 gene in a dog with a novel form of ichthyosis." (PMID 28249031, 2017). "Thus, the increased ASPRV1 quantity is at least compatible with a causal role of the ASPRV1 missense variant in the observed ichthyosis." (PMID 28249031, 2017). "Thus, our findings provide strong evidence that the identified de novo variant is causative for the ichthyosis in the affected dog and that ASPRV1 plays an essential role in skin barrier formation." (PMID 28249031, 2017). "Thus, our results strongly suggest that genetic variants in ASPRV1 can cause ichthyosis by altering filaggrin processing." (PMID 28249031, 2017). "It seems possible that ASPRV1 variants might also contribute to unsolved human ichthyoses." (PMID 28249031, 2017). "Some mutations of ASPRV1 were found to impair its proteolytic activity and result in the accumulation of unprocessed pro-FLG, even causing a deficiency of skin hydration (ichthyosis)." (PMID 39098535, 2024). "The role of ASPRV1 in skin regeneration was also proved using a mouse model, and correlations of ASPRV1 with ichthyosis have also been reported; both dog and human variations were found to have role in the development of this skin disorder." (PMID 32640672, 2020). "According to our knowledge, the ASPRV1 gene has not been associated with any form of ichthyosis in humans." (PMID 28249031, 2017). "ASPRV1 is thus a novel candidate gene for unexplained human forms of ichthyoses." (PMID 28249031, 2017). "Most well documented forms of canine ichthyosis are non-epidermolytic, involving genetic variants in ABHD5 or PNPLA1 in golden retrievers, TGM1 in Jack Russell terriers, NIPAL4 in American bulldogs, and ASPRV1 in a German shepherd dog." (PMID 36251712, 2022).
atopic dermatitis (3 papers, 2017 to 2024). "Missense variants in the human ASPRV1 gene were reported in 5 of 196 Japanese patients with atopic eczema and 2 of 28 control subjects." (PMID 28249031, 2017). "Two of the identified variants, p.V243A (identified in a control subject) and p.V187I (identified in 3 atopic eczema patients) led to absence or reduction of ASPRV1 activity in vitro." (PMID 28249031, 2017).
encephalomyelitis (1 paper, 2020). Inflammation of the brain and the spinal cord. "Sensitivity of ASPRV1 towards protease inhibitors may also contribute to the better understanding of enzyme regulation in the treatment of skin disorders and chronic inflammatory autoimmune diseases such as MS and encephalomyelitis." (PMID 32640672, 2020).
melanoma (1 paper, 2025). A malignant, usually aggressive tumor composed of atypical, neoplastic melanocytes. "Moreover, the rest of SASP-related genes recruited in our risk-scoring model including HLA-B, TPMT, ATM, CD59, TRIM21, and ASPRV1 have not been well studied in melanoma, indicating their potential of novel therapeutic target." (PMID 40864319, 2025).
retinitis pigmentosa (1 paper, 2021). Retinitis pigmentosa (RP) is an inherited retinal dystrophy leading to progressive loss of the photoreceptors and retinal pigment epithelium and resulting in blindness usually after several decades. "ASPRV1 associated diseases include retinitis pigmentosa and artrichia with papular lesions." (PMID 34179686, 2021).
skin disorder (2 papers, 2017 to 2020). Any deviation from the normal structure or function of the skin or subcutaneous tissue that is manifested by a characteristic set of symptoms and signs. "Furthermore, high ASPRV1 protein levels were present in several non-neoplastic skin disorders." (PMID 28249031, 2017).
tumor (2 papers, 2024). "Based on PhosphoSitePlus database ASPRV1 mutations can be detected in tumor samples, but only with very low frequency, the highest frequency was found in colorectal, endometrial, and squamous lung is <1.5%, indicating no oncogenic potential for ASPRV1 mutations." (PMID 39098535, 2024). "Among the downregulated DEGs, four genes (LAMA1, ASPRV1, IL1B, PRR4) displayed reduced expression, while two genes (CCDC157, RP1) showcased elevated expression in tumor compared to normal tissue, respectively." (PMID 39062832, 2024).
cancer (1 paper, 2024). A tumor composed of atypical neoplastic, often pleomorphic cells that invade other tissues. "The changes of ASPRV1 expression in various cancer types along with the identified non-synonymous variants causing mutation of the protein are available in the TissGDB (Tissue specific Gene DataBase in cancer) database." (PMID 39098535, 2024).
immune disorders (1 paper, 2020). "While some functional properties have already been revealed, further characterization of ASPRV1 is justified by its potential importance in the development and treatment of some skin and immune disorders, including MS." (PMID 32640672, 2020). "Inhibition studies on ASPRV1 may help to understand its contribution to skin barrier dysfunction, the herein described sensitivity of the enzyme to protease inhibitors reinforces the interest in studying how ASPRV1 could be potentially targeted in the treatment of immune disorders, including MS." (PMID 32640672, 2020).
inflammation (1 paper, 2023). Aberrant reaction of the microcirculation characterized by movement of fluid and leukocytes from the blood into extravascular tissues. "For instance, a large number of NE1 cells were expressed with mature neutrophil markers (e.g., Retnlg, Lcn2, and Asprv1, associated with chronic inflammation), while NE2 cells were highly expressed with pro-inflammatory molecules (e.g., Tnf, Il1b, and Nlrp3, which trigger acute inflammation)." (PMID 37781362, 2023).
ASPRV1 also shares sentences with these, for which no sentence is quoted: lung carcinoma (1 paper).